IFNG (interferon gamma)
Diseases named in the same sentence as IFNG in open-access papers (continued):
Sharing a sentence is not in itself a finding about the gene and the disease.
tumor (continued). "In addition to inhibiting cell proliferation, angiogenesis, and increasing MHC surface expression, IFNγ was also shown to contribute to upregulation of TRAIL expression on NK cells, which suggests that one mechanism may interact with another to synergistically enhance tumor killing." (PMID 26284063, 2015). "The increased immunization dosage shows a significant impact on the length but not the collective magnitude of Interferon gamma (IFNG) and Tumor Necrosis Factor alpha (TNF α) in the tumor microenvironment." (PMID 26048402, 2015). "In WT mice receiving Fab anti-CD200R, no tumor cells are detectable following immunotherapy, and CD4+ cells produced increased TNFα/IL-2/IFNγ on stimulation with EMT6 in vitro." (PMID 25409195, 2014). "In response to further in vitro stimulation with tumor antigen (Tum-Ag) and tumor microenvironmental antigen (TME-Ag), there is enhanced IFNγ secretion with or without NLGP supplementation." (PMID 23326300, 2013). "To date, no defined tumor antigen has been identified on RENCA cells; therefore, an indirect assay to quantitate IFNγ expression was established using culture supernatants of purified splenic and hepatic T cells co-cultured with irradiated RENCA tumor cells." (PMID 22428016, 2012). "There was no induction of IFNγ expression in any type of parental or bystander normal BJ cells, but there was an increase in parental drug-induced senescent U2OS tumor cells, which correlates with increase of IFNγ secretion in this cell line." (PMID 23385065, 2012). "The increased expression of IFNγ in the bladder at day 7 is probably due to CXCL10 being secreted by the tumor cells, but MB49 itself does not express IFNγ." (PMID 22013484, 2011). "In contrast, IFNγ/STAT1 signaling and autophagy are not activated in tumor cells from the lungs of therapeutically treated mice." (PMID 21931823, 2011). "The finding that ESCC tumor cell lines show no constitutive IDO expression and that only IFNγ was able to induce huge activity corresponds very well to early Werner-Felmayer's study, but is a little against claims made by Uyttenhove." (PMID 22013481, 2011). "Comparable data were obtained after injecting tumor-bearing TRAMP mice with α-GalCer with and without the addition of recombinant IL-12 showing a significant increase of IFNγ serum levels in response to α-GalCer and IL-12 compared to α-GalCer alone." (PMID 20593019, 2010). "The tumor-specific T cells induced from both PBMC and TIL (not shown) secreted IFNγ when co-cultured with T2 cells loaded with the relevant but not with a control peptide." (PMID 20454561, 2010). "Importantly, this effect was not specific to the progressing B16‐cOVA tumor, as OT‐I cells responding within the context of TFLN to established D5.1G4‐cOVA (both 7‐ and 14‐day‐old tumors) failed to fully differentiate into IFNγ‐secreting effectors as well." (PMID 39930625, 2025). "Intrinsic resistance may stem from tumor-intrinsic factors such as low TMB, lack of neoantigen presentation, or defective interferon-gamma signaling pathways." (PMID 40299523, 2025). "Within the tumor microenvironment (TME), 4-OI reduced the frequencies of CD8+ and IFNγ+ CD8+ T cells, but had no significant impact on CD4+, Foxp3+ CD4+ T cells, or myeloid-derived suppressor cells (MDSCs), including monocytic (M-MDSC) and granulocytic (M-MDSC) subsets." (PMID 40521193, 2025). "Although vaccine delivery using the Oligomer scaffold elicited significantly higher antibody responses and IFNγ+CD4+ T cells, a limitation of this study is the lack of direct evidence demonstrating the effectiveness of these responses against viral or tumor challenges." (PMID 41295519, 2025). "In conclusion, our current study demonstrates a novel mechanism of suppression of alternative NF-κB by IFNγ that selectively promotes the expression of CTL-attracting chemokines and recruitment of CTLs by tumor-resident myeloid cells without the recruitment of Tregs." (PMID 41142824, 2025).
tumor (continued). "In addition, the TSH‐28ζ‐CAR‐T and TSH‐BBζ‐CAR‐T cells produced substantial amounts of IFNγ and IL‐2 when coculturing with TSHR‐positive tumor cells, while no cytokines were released in the coculture with WT tumor cells." (PMID 40985353, 2025). "Co-culture with B16 ffLuc GFP EGFR cells for 24 h induced the secretion of approximately 4 pg/mL of IL-2 and 3.5 × 103 pg/mL of interferon-gamma (IFN-γ) by EGFR mCAR T cells, while no significant cytokine release was detected in cultures without antigen-positive tumor cells." (PMID 41516067, 2025). "DC matured by co-culture with 1B3-transfected HCT116 induced production of the type 1 cytokines IFNγ and TNFα, and proliferation (expressed as percentage CTVlow cells) by CD4+, CD8+, and CD4-CD8- T cells whereas DC matured by mock or 3A1-transfected tumor cells had no or limited effect." (PMID 39007281, 2024). "Administration of anti-PD-L1 antibodies to isolated, tumour antigen-experienced CCR7+ BMDC in vitro did not alter their phenotype, but the addition of recombinant IFNγ upregulated expression of OX40L, PVR and CD40, consistent with the activated Ccr7_DC.2 state." (PMID 38267413, 2024). "Unlike CD8-targeted tracers, 89Zr-anti-IFNγ can directly represent effector function, addressing the limitation that CD8+ T cells might become dysfunctional despite the presence of tumor-infiltrating lymphocytes." (PMID 39072335, 2024). "Indeed, we found high levels of IFNγ secretion by both aEGFRvIII and aEGFRvIII-SGRP CARs in vitro and in vivo but only SGRP-armored CARs were able to cope with a high tumor load of target-negative cells in vivo." (PMID 39521782, 2024). "Multiple mechanisms likely contribute to the improved efficacy of SGRP-secreting CAR T cells, and potential cooperation between SGRP, IFNγ, and CCL3-like chemoattractants might be crucial to eliminate bystander antigen-negative tumor cells." (PMID 39521782, 2024). "Differential gene expression showed an enrichment of genes involved in T cell recruitment (CXCL9, CXLC10) and interferon-gamma activity (GBP1, STAT1) in the macrophage compartment of responding tumours, while non-responders were enriched in immunosuppressive markers (GPNMB, CCL18)." (PMID 38030622, 2023). "As expected, tumor tissues of untreated PDX mice expressed CA19-9, but not IFNγ." (PMID 38136341, 2023). "Similarly, we did not observe any difference in IFNγ or TNFα production between TIGIT+ and TIGIT− NK cells in response to cytokine stimulation, suggesting that these TIGIT+ NK cells have greater anti-tumor but not general responsiveness." (PMID 37345049, 2023). "Another study by Zhang and colleagues reported that CD8 + T cells and NK cells could evoke pyroptosis of tumor cells independent of caspases through the GSDME-GZMB axis, which is induced by interferon-γ (IFNγ)." (PMID 37730669, 2023). "Two days after treatment initiation, interferon gamma (IFNG, best known as IFNγ) and interleukin 2 (IL2), which are produced upon CAR T cell activation, became detectable above background in ALL-bearing (but not tumor-naïve) mice receiving CAR T cells (but not in mice treated otherwise)." (PMID 37142568, 2023). "Furthermore, both Breg subsets from tumor-bearing mice treated with Rat IgG, but not those treated with GSK, showed stronger inhibition on IFNγ production by CD4 T cells than the Breg counterparts from naïve mice." (PMID 37291146, 2023). "CD96 deficiency reduced the frequencies of NUR77-, T-bet-, TNFα- and IFNγ-expressing tumor-specific CD8+ T cells in a mouse model of colorectal carcinoma, suggesting CD96 co-stimulated rather than inhibited effector T cell anti-tumor responses." (PMID 36672244, 2023). "Conversely, introducing a drug-resistant SHP2 mutant into tumor cells did not elevate MHC class I levels when treated with SHP099, confirming that the heightened IFNγ signaling induced by SHP099 in cancer cells is directly attributable to the targeted inhibition of SHP2." (PMID 38001644, 2023).
tumor (continued). "Although tumour growth was not significantly inhibited by napabucasin (data not shown), LAG‐3+ and Tim‐3+ CD8+ T cells were significantly reduced, while the expression of IFNγ was significantly increased." (PMID 35665592, 2022). "None of the DC loaded with tumor lysate, EpiTCer beads or EpiTCer WT bead, stimulated CD8+ T cell populations displayed an efficient recognition of the autologous monocytes, measured by degranulation or IFNg production." (PMID 35433456, 2022). "DuoBody-CD3x5T4–induced TIL-mediated tumor cell kill was also associated with dose-dependent production of IFNγ and GZMB; no IFNγ and GZMB production was observed when DuoBody-CD3x5T4 was incubated with the 5T4− LU1 tumor sample, in line with the absence of kill." (PMID 36271507, 2022). "In addition, tumor tissue showed an increase in heparanase, MMP9, PPARγ, and IFNγ, while non-tumor adjacent tissue showed an increase in E-cadherin and COX2 and a decrease in IL-4R." (PMID 36139645, 2022). "This study did not evaluate MHC class II, that correlates with reduced tumor growth in our study more than class I. Similarly, Ca alone resulted in increased frequency of CD8+ IFNγ+ T cells, decreased myeloid cells, and increased Tregs in both human and mouse models." (PMID 36419897, 2022). "However, there is no overlap in Vβ usage between IFNγ+CD8+ T cells in colon, systemic circulation, and tumor, indicating that these IFNγ+CD8+ T cells are induced locally and independently." (PMID 35355998, 2022). "To further corroborate the relationship between CD4 T-cell activation and tumor burden, we performed an unbiased correlation analysis of all the treated tumor samples for tumor burden and CD4 T IFNγ+ cell frequency and found a strong negative correlation between these two parameters." (PMID 35651802, 2022). "Like cytokine-polarized TAMs and MDSCs, we found that tumor-cell-differentiated MARCO+ TCM, independent of cell-to-cell contact, could suppress cytotoxic T cell and NK cell IFNγ production, proliferation, and/or degranulation (CD107a)." (PMID 36310582, 2022). "Additionally, an acidic TME has been associated with decreased IFNγ production by NKs and enhanced tumor growth, suggesting that the TME is often not optimized to support IFNγ-mediated immune activity." (PMID 33801234, 2021). "Although the induction of anti-tumor T-cell responses, including upregulation of IFNγ and GzmB on CD8+ T-cells, in irradiated tumors has been detected, the proper trafficking of effector T-cells into the tumor microenvironment may not always occur." (PMID 33419318, 2020). "There was no increase in tumor infiltrating CD8+ T cells expressing “exhaustion” markers, yet oHSV infection led to a reduction in PD-1+ CD8+ T cells in injected GBMs and an increase in IFNγ+ CD8+ T cells." (PMID 32198420, 2020). "As tumor-infiltrating lymphocytes (TILs) are a predominant source of IFNγ, they might upregulate IDO as a negative feedback signal, hereby potentially contributing to tumor immune escape." (PMID 33072086, 2020). "Our results also showed that tumour infiltrating CD4+ and CD8+ T cells isolated 3 weeks after TC-1 tumour inoculation secrete less IFNγ compared with those isolated at 3 weeks, whether or not the T cells express PD-1." (PMID 31277636, 2019). "Moreover, MAPK pathway inhibition using erlotinib and selumetinib did not influence IFNγ‐induced upregulation of MHC‐I expression, suggesting that MHC‐I‐mediated tumor cell antigen presentation will not be impaired by these drugs." (PMID 30972766, 2019). "Similarly, NK cells cultured in the absence of tumour cells for 18 h and then provided IL2 for 18 h did not produce IFNγ." (PMID 31595191, 2019). "Interferon-γ (IFNγ) secretion and activation marker expression was decreased in stimulated Jurkat T-cells when co-cultured with HK2-overexpressing vector-transfected tumor cells rather than empty vector-transfected tumor cells." (PMID 31718692, 2019).
tumor (continued). "Our data suggest that CD56bright NK cells may have a negative effect on the anti-tumour response by inhibiting T cell responses, via CD38, perforin, CD11a and IFNγ." (PMID 30872676, 2019). "Using CD3+/CD28+ T cells isolated from immune competent mice, we observed that NextA did not induce major changes in the production of either IFNγ and IL2, implying that the anti-tumor activity of HDAC6i was not mediated by the direct action of this drug on T cells." (PMID 30992475, 2019). "Nonetheless, in the DEN-induced HCC model, CD8+ T cells produced IFNγ and TNF-α, but not IL-17; CD4+ T cells, however, were a potential source of IL-17 and could be acting as a subset with pro-tumor function (unpublished)." (PMID 30150983, 2018). "We show a decreased ratio of IFNγ+ to FOXP3+ cells in CD4+ TILs lacking HIF-1α, which could further contribute to the observed accelerated tumor growth." (PMID 29136509, 2017). "Interestingly, in the exhausted state, CTLs may exhibit residual IFNγ production, albeit at low levels, but may express high levels of granzyme B with some residual cytotoxic capacity, although these studies were conducted by examining chronic viral infection, not the tumor microenvironment." (PMID 29088901, 2017). "Indeed, in the presence of SKBR3 tumor cells coated with αGC/sCD1d-anti-HER2, about half of iNKT cells was positive for TNFα and IFNγ, while no intracellular cytokines were detected in the presence of the irrelevant αGC/sCD1d-anti-CEA fusion protein." (PMID 23242316, 2013). "Collectively, these data suggested that tumor cells, although up-regulating activation markers on type-I NKT cells (in particular the IL-12 receptor) inhibit complete responses, observed as a lack of IFNγ production." (PMID 24212972, 2011). "Therefore, IFNγ bystander signaling, which has been recently reported to influence tumor cells multiple cell layers beyond CTL-rich regions, is essential to maintain residual tumor cell quiescence including nonantigenic cells in coculture." (PMID 40166148, 2025). "Thus, we believe that pruning of dysfunctional non-HEV tumor blood vessels upon anti-CTLA-4 treatment, resulting from the anti-angiogenic effects of IFNγ, will lead to an increased functionality and a better perfusion of the remaining vessels, including TA-HEVs." (PMID 40460830, 2025). "Moreover, we conducted in vitro experiments to prove that, exogenous overexpression of GBP5 in T cells fails to augment their tumor-killing efficacy, while elevated GBP5 expression in OC cells does not directly enhance the secretion of GZMB and IFNγ from T cells." (PMID 38817865, 2024). "Interestingly, in WT mice receiving EMT6 and Fab anti-CD200R, no tumor cells were detectable after immunotherapy (tumor cell vaccination), and the CD4+ cells produced increased TNFα/IL-2/IFNγ on stimulation with EMT6 in vitro, as had been seen already in CD200RKO mice." (PMID 38540350, 2024). "However, treatment of ITF2357, I‐BET151, or JQ1 only on T cells directly isolated from the OT‐I mouse spleen did not increase the secretion levels of IFNγ, GZMB, or TNFα, suggesting the drug effects are dependent on the interaction of T cells with the tumor or other stroma cells in the organoids." (PMID 37271874, 2023). "We found a negative correlation between tumour necrosis percentage and CXCL10 concentrations in mesenteric venous serum (beta = −0.460, P = 0.022), and a trend towards a negative correlation between tumour necrosis percentage and IFNG (beta = −0.363, P = 0.076)." (PMID 37031328, 2023). "However, the median fluorescence intensity (MFI) of MHC-I-positive staining was significantly lower in FAK-wt tumours when compared with FAK-/- tumours, irrespective of IFNγ treatment, supporting in vitro findings that FAK loss upregulates MHC-I expression on the cell surface." (PMID 36977556, 2023).
tumor (continued). "However, the peripheral serum IFNγ and granzyme B measurements did not closely reflect KD033 activity in the tumors as the magnitude of increases did not correlate to the observed anti-tumor activity levels." (PMID 36454338, 2023). "To understand whether the macrophage mode of activation changes the effects they exert on the tumor cells, we activated RAW 264.7 macrophages for 24 h as M0 (no treatment), M1 (incubation with 100 U/mL IFNγ and 100 ng/mL LPS) or M2 (incubation with IL-4 and IL-13, 20 ng/mL each)." (PMID 36979746, 2023). "Cluster 6 and Cluster 3 were not adjacent, but similar tissue (tumor) activated the same pathways (Estrogen Response Early, Epithelial-Mesenchymal Transition, Allograft Rejection, Inflammatory Response, TNF-alpha Signaling via NF-kB, and Interferon Gamma Response)." (PMID 35260632, 2022). "They found common transcriptional pathways that were upregulated in the tumor, stroma, and CD4 T cell populations of ERG negative patient tumors, including the PD-1 and IFNγ signaling pathway, suggesting that ERG tumor cells may give rise to a distinct immune cell niche in the TME." (PMID 34502458, 2021). "Pt32, who could not undergo surgery, had a baseline tumor characterized by a high CPS, but low TMB (80, trial median 172), low baseline IFNγ gene expression (Z-score −0.92, trial median −0.26) and low intratumoral CD8 + T-cells (41.7, trial median 83.8 cells/mm2)." (PMID 34937871, 2021). "Gene expression analysis of the tumor further supported the phenotypic analysis in both PD-1cKO- and PD-1 Ab-treated mice and showed an upregulation of pathways related to CD4 and CD8 T-cell activation, enhanced signaling through costimulatory molecules and IFNγ, and non-T-cell processes." (PMID 34912335, 2021). "As for T cell related cytotoxins, essential in tumor killing, stacked FPKM of 8 genes (PRF1, GZMM, GZMK, GZMH, GZMB, GZMA, FASLG, and FAS) demonstrated that these genes were more highly expressed 1.7-fold (P = 0.037) in IFNγ positive tumors compared to IFNγ negative tumors." (PMID 32265897, 2020). "The intracellular expression of IFNγ in either CD4+ or CD8+ T cells remains unchanged between shScr-ST and shIDO-ST-treated groups, which may explain the lack of tumor control by sub-therapeutic doses of shIDO-ST alone." (PMID 33339195, 2020). "The expression of immune-modulating cytokines IL-6, TNFα and interferon gamma (IFNγ) was not significantly altered by the combination of cisplatin and P-MAPA, yet P-MAPA alone increased IFNγ expression in the OC tissues which can elicit anti-tumor immune responses by activation of innate immunity." (PMID 31443240, 2019). "While we were unable to rule out a contribution of other IFNγ-producing cells in our observations, it is notable that we identified a strong correlation between the ability of different chemotherapies to induce CD8 T cell infiltration in the tumor in vivo and the induction of PD-L1 tumor expression." (PMID 31191545, 2019). "We wish to investigate whether blocking IL-10 at the time of immunisation, which increases the numbers of antigen specific IFNγ CD8+ T cells, better prevent TC-1 tumour growth in mice than immunisation without IL-10 signalling blockage, especially in therapeutic setting." (PMID 31277636, 2019). "The treatment of tumor cells with IFNγ removes the silencing of GPR109A without changing the methylation of its promoter, suggesting that histone acetylation may be critical in the IFNγ-induced expression of GPR109A." (PMID 31121824, 2019). "An important prerequisite for antigen-specific immune recognition and tumour cell elimination is the sufficient expression of HLA molecules, in especially class I. In both HROC69 cell lines, HLA class I was barely expressed and even IFNγ pre-treatment did not increase expression." (PMID 27087592, 2016).